BRD4 (bromodomain containing 4)
Diseases named in the same sentence as BRD4 in open-access papers (continued):
Sharing a sentence is not in itself a finding about the gene and the disease.
cancer (continued). "Although BRD4 has been demonstrated to act as a potential therapeutic target for several cancers, it has not yet been investigated in GC." (PMID 28415703, 2017). "Our data show that combined inhibition of BRD4 and CHK1 produces maximal cytotoxic effects at reduced dosages, potentially reducing side effects of either drug and increasing the therapeutic index for cancer treatment." (PMID 28881656, 2017). "The recent identification of Brd4 inhibitors including JQ1 and I-BET provides great potential for treatment of HPV-induced cancers as both inhibitors target bromodomains and prevent them from binding to acetylated histones and to act as transcriptional activators." (PMID 26727473, 2016). "Interestingly, in basal-like breast cancer, an acetylatable histone H4 mimic motif within the oncogenic transcription factor TWIST can recruit BRD4 and activate transcription of WNT5A, which correlates with an aggressive cancer phenotype." (PMID 27223260, 2016). "Further studies are essential to determine how often Brd4 activates viral transcription in HPV infections and cancers, and if this is widespread, iBET inhibitors could be therapeutic for a wide range of HPV-associated diseases." (PMID 27624132, 2016). "BRD4 inhibition by JQ1 is an emerging and relevant target for the treatment of various cancers." (PMID 24576043, 2014). "Members of the bromodomain and extra-terminal domain (BET) family, especially bromodomain-containing protein 4 (BRD4), play important roles in RNA polymerase II-mediated transcriptional regulation and are required for the expression of many tumor-driving oncogenes in various cancer cells." (PMID 42224297, 2026). "Notably, however, ARV-771 has been demonstrated to overcome radioresistance in some cancer types, thereby suggesting that targeting BRD4 can effectively regulate gene expression regardless of the specific transcription factor involved." (PMID 41614901, 2026). "The presence of focal deletions spanning BRD4 regulatory regions suggests that these rearrangements may mechanistically reduce gene expression to levels that are no longer toxic to cancer cells." (PMID 40112818, 2025). "We hypothesized that BRD4 is initially amplified in cancer cells, but high expression levels are not tolerated." (PMID 40112818, 2025). "However, most of the current research on BRD4 degraders has not yet entered the clinical trial stage, and numerous experiments are still required to verify its development into a mature anti - cancer drug and its market launch." (PMID 39838405, 2025). "BRD4-NUT recognizes acetylated chromatin and binds acetyltransferase p300 to form condensates, inducing histone hyperacetylation and chromatin subcompartment that sustain aberrant anti-differentiation genes transcription and perpetual tumor cell growth in midline carcinomas." (PMID 40507965, 2025). "AT1 significantly degraded BRD4 (DC50 = 10-100 nM, Dmax > 90%) in all tested cancer cells; however, it showed negligible activity against BRD2 and BRD3, suggesting that AT1 demonstrated a greater degree of selectivity in its ability to deplete BRD4 compared to MZ1." (PMID 38389844, 2024). "Thus, BRD4 inhibitors might be more effective in combination with ferroptosis inducers, especially in FSP1-dependent cancer cells." (PMID 38565708, 2024). "Although BRD4 has been recognised as a potential target for cancer therapy, none of the BRD4 inhibitors in current clinical trials have received approval from the United States Food and Drug Administration (FDA) for human use due to ‘off‐target’ effects and induced drug resistance." (PMID 38303608, 2024). "Notably, the data suggest that MYC synthetic lethality is not necessarily contingent on simultaneous overexpression of both targets but rather, endogenous levels of molecular nodes such as BRD4 and CHK1 become critical to the survival of MYC‐addicted cancer cells." (PMID 36684069, 2023).
cancer (continued). "However, the expression of BRD4 has not been reported for the individual cancer stages of patients with ACC." (PMID 36793283, 2023). "As a result of the fact that BRD4 demonstrates YAP/TAZ‐independent transcriptional activity, combined YAP/TAZ/BRD4 targeting could also address the full extent of the tumour mechanosignaling‐engaged impact on cancer progression." (PMID 37994501, 2023). "Bromodomain containing protein 4 (BRD4), a member of thebromodomain and extraterminal domain (BET) family of proteins which bind toacetylated histones, modulates cell cycle progression and inflammation, amongothers, and has been studied extensively in cancer biology." (PMID 36875282, 2022). "Because an increasing number of studies have shown that BRD4/BET inhibitors and kinase inhibitors might act synergistically in a range of cancer types, the predicted off-target interactions with kinases might provide clues and starting points for further study of related dual functional inhibitors." (PMID 34677780, 2022). "When cancer cells undergo PCD, the expression of Brd4 may be further changed." (PMID 36539410, 2022). "Our study identifies RB protein as a bona fide intrinsic inhibitor of BRD4 and demonstrates that RB inactivation confers resistance to small molecule BET inhibitors, thereby revealing a regulatory hub that converges RB upstream signaling onto BRD4 functions in diseases such as cancer." (PMID 36274096, 2022). "Especially, the engagement of BRD4, a member of BET transcriptional coactivators, as well as the role for TRIM28—a transcriptional co‐repressor, known to mediate E3 SUMO/ubiquitin ligase activity, have been well established in mediating the self‐renewal properties of cancer stem cells." (PMID 35049055, 2022). "A subsequent study used publicly available transcriptional profiling data to demonstrate that BRD4 inhibition modulates a previously validated HR defect gene signature, though finding minimal impact on BRCA1 or RAD51 expression in cell lines of multiple cancer types." (PMID 35681619, 2022). "This correlation suggests that the regulatory mechanism of BRD4 on KEAP1 and G6PD may be beyond SCLC and may exist in a variety of cancers which provides a new basis for overcoming drug resistance to BETis in other cancer types." (PMID 35453346, 2022). "Moreover, BRD4, a member of the bromodomain and extra-terminal domain (BET) protein family, plays a pivotal role in promoting DNA repair as well as regulating super-enhancers and transcriptional activation of oncogenes in cancer." (PMID 35204785, 2022). "However, for high-risk HPV types (those that cause cancer, including HPV16), there have been reports that E2 and BRD4 do not colocalize on mitotic chromatin, suggesting that BRD4 is not the primary mitotic chromatin receptor for these HPV E2 proteins." (PMID 35880889, 2022). "While BRD4 is the most studied among BET proteins, there are several reports indicating that BRD2 and BRD3 might also play an important role in dysregulating oncogenes in cancer." (PMID 34440844, 2021). "Therefore, inhibiting CDK9, BRD4 and SEC in combination could prove to be a highly effective trident of inhibitors against cancers, especially against the cMYC driven ones." (PMID 34062779, 2021). "Thus, drugs such as BRD4 inhibitors that target the upstream pathways regulating MYC may be attractive candidates to control the metabolism and growth of chemoresistant cancer cells." (PMID 34031395, 2021). "For high-risk HPV (HR-HPV) (those that cause cancer, including HPV16), the E2 proteins do not colocalize with BRD4 on mitotic chromatin, indicating that BRD4 may not be the mitotic receptor for these E2 proteins." (PMID 34544280, 2021).
cancer (continued). "Therefore, inhibition of BRD4 activity could suppress MYC transcription pathway activity and then block the process of cancer development." (PMID 34733788, 2021). "Considering the inhibitory effect of Brd4 inhibition on CD8+ T cells function and differentiation, it could not be feasible to combine Brd4-targeting therapy with CAR-T-/TCR-T-based immunotherapy for incurable cancer." (PMID 34512660, 2021). "Of interest, BRD4 is highly enriched in super-enhancers that drive the expression of oncogenic transcription factors such as c-Myc, suggesting that targeting BET family proteins could be a promising approach for cancer treatment." (PMID 33916219, 2021). "Additionally, unlike CDK9, the genetic alterations of BRD4 also occur with increasing frequencies in different cancer entities." (PMID 34062779, 2021). "Our results demonstrate that BRD4 is a critical regulator of Hippo/YAP1 signaling and that BRD4 inhibitor JQ1 represents a new class of inhibitor of Hippo/YAP1 signaling, primarily targeting YAP1 high and therapy‐resistant cancer cells enriched with cancer stem cell properties." (PMID 32175692, 2020). "Bromodomain containing 4 (BRD4), a member of the bromodomain and extraterminal (BET) protein family, interacts with the acetylated lysine residues of histone tails on chromatins and consequently promotes several oncogenic transcriptions such as c-MYC, which contributes to cancer cell proliferation." (PMID 32184777, 2020). "Hence, it has been challenging to develop anti-cancer strategies that specifically target BRD4 oncogenic activity without affecting its normal function in noncancerous cells." (PMID 32575711, 2020). "Therefore, targeting BRD4, is one of the strategies to target Myc and several BET inhibitors such as BMS-986158, RO6870810, and GSK525762 are in different phases of preclinical and clinical trials for the treatment of different cancers." (PMID 32824207, 2020). "Furthermore, our results suggest that CDK1-mediated BRD4 hyperphosphorylation contributes to BETi resistance, and that inhibition of CDK1 could synergistically work with BETi to more effectively kill cancer cells." (PMID 32575711, 2020). "The BET proteins comprise a family of four proteins: BRD2, BRD3, BRD4, and BRDT, which use two tandem BRD domains to recognize N-acetylated lysine residues to recruit transcription factors, both in physiological and disease processes such as inflammation and cancer." (PMID 31226848, 2019). "In addition, some researchers have proposed a non-transcriptional role of BRD4 in activation and repair of DNA damage checkpoints and telomere maintenance, opening new perspectives on the use of BETi in cancer." (PMID 31105558, 2019). "BETi mediated inhibition of these BRD4 non-canonical activities could significantly impact on cancer cells growth and survival." (PMID 30466442, 2018). "Intensive research in the cancer field has unraveled the role of BET proteins in NF-κB pathway regulation, demonstrating that BRD4 binding to acetylated lysine-310 of RelA is essential for recruiting BRD4 and CDK9 to the promoters of specific NF-κB target genes." (PMID 30647531, 2018). "Because the inhibition of BRD4-mediated recruitment P-TEFb to MYC and other PRGs by JQ1 and iBET-151 can suppress cancer growth and progression, it is tempting to speculate that the direct inhibition of P-TEFb itself will produce a similar or perhaps even more focused effect." (PMID 26083714, 2015). "To confirm whether this negative correlation between GDF15 and GDF11 is the result of target-specific inhibition of BRD4 or due to a non-specific effect of the drug on other targets, we looked up literature for gene expression profiling after BRD4 gene knockdown in cancer cell lines." (PMID 37495707, 2023). "However, the interactions between BRD4 and SWI/SNF as well as FET‐FOPs are not clearly defined, and how BRD4 contributes to oncogenesis in FET‐FOP‐caused cancer is still unknown." (PMID 35182012, 2022).
cancer (continued). "Bromodomain-containing protein 4 (BRD4) is an important member of the Bromo and Extra-Terminal (BET) family, the bromodomains of which may bind to acetylated histones and transcription factors to regulate multiple pathophysiological activities including cancer and inflammation." (PMID 33679744, 2021). "Finally, we found that JQ1 treatment induced ferroptosis by suppressing BRD4 expression via the inhibition of the histone methylase G9a or activation of the histone deacetylase SIRT1 as there are enhanced H3K4me3 and H3K27ac levels at upstream of BRD4 in cancer." (PMID 30988278, 2019). "The evidence that BRD4 positively regulates DNA damage checkpoint activation and DSB repair, implicates that its pharmacological inhibition by BETi may increase sensitivity of cancer cells to DDR or ATR inhibitors defining a possible combination strategy in specific tumor settings." (PMID 30466442, 2018). "Taken together, these results strongly supported the excellent anti-cancer effects of BRD4 inhibition by JQ1 in sunitinib-resistant ccRCC and suggested that SCG5, SPOCD1, RGS19, and ARHGAP22 may be novel direct targets of the epigenetic reader BRD4 in sunitinib-resistant ccRCC." (PMID 29796168, 2018). "Together these results show that 105B is highly potent in two cancer cell lines expressing MAGEA11 and demonstrates no BRD4 degradation in HEK293T cells." (PMID 41279184, 2025). "Recent studies indicate that regardless of BRCA1/2 status, inhibiting BRD4 with BETi decreases the expression of the DNA repair factor CtIP, inducing HR defects and enhancing DNA damage induced by PARP inhibitors in cancer cells." (PMID 39156700, 2024). "However, further experiments and many more investigations are needed to confirm this first data set and to transfer it to other NC cancer cell lines, including those that do not carry BRD4 as a fusion partner, which may uncover additional co-actors and novel therapeutic targets." (PMID 38793657, 2024). "This modification served as the activating component for click-release of PROTAC prodrugs, enabling targeted degradation of BRD4 and B-Cell Lymphoma-XL (BCL-XL) proteins in cancer cells while sparing noncancerous normal cells." (PMID 38773495, 2024). "Thus, for example, if loss of SAGA or BRD4 in human cells render cells lacking TORC2 resistant to stress, treating cancer cells that have lost TORC2 signaling with drugs that inhibit SAGA or BET family proteins may result in adverse effects of chemotherapy resistance." (PMID 35157728, 2022). "The interaction between p65 and BRD4 has previously been observed in HEK293T and A549 cancer lines but not in β-cells." (PMID 36176467, 2022). "Consistently, our correlation analyses confirmed that the normalised BRD4 and MMP2 expression levels were correlated in cancer tissues but not in non-cancer tissues." (PMID 32499570, 2020). "As opposed to BRD4, BRD9 is a selective dependency in certain cancer types, including AML and synovial sarcoma." (PMID 33371192, 2020). "Surprisingly, they found that due to a tumor protection mechanism controlled by BRD4 (Bromodomain-containing protein 4), cells from HGPS patients typically do not develop cancer." (PMID 33163298, 2020). "Indeed, a non-transcriptional role of BRD4 in controlling DNA damage checkpoint activation and repair as well as telomere maintenance has been proposed, throwing new lights into the multiple functions of this protein and opening new perspectives on the use of BETi in cancer." (PMID 30466442, 2018). "Most (but not all) studies have shown that anti-tumorigenic effect of BRD4 inhibition is through the antagonization of MYC, which is the most well-known oncogene in several cancers." (PMID 27081696, 2016).
cancer (continued). "Notably, AZD5153, a bivalent BRD4 inhibitor, displayed desirable safety and efficacy profile in phase II clinical trials for non-NEPC cancer types." (PMID 40370549, 2025). "Hence, the genetic suppression of BRD4 fails to mimic the effect of JQ1 in decreasing c-FLIP and sensitizing cancer cells to TRAIL-induced apoptosis." (PMID 26415225, 2015). "In fact, the non-transcriptional role of BRD4 in controlling DNA damage checkpoint activation and repair, as well as telomere maintenance, has been proposed, providing a new perspective on the multiple functions of the protein and opening up new prospects for BET inhibitor’s application in cancer." (PMID 32099528, 2020). "Interestingly, ROS1 and BRD4 KGFs occur at four different breakpoint sites; conversely, ALK and RET are found rearranged using the same breakpoint in different cancer cell line models, regardless of the cancer type context." (PMID 33257674, 2020). "Therefore, targeting EGFR may not be the best course of therapy for certain cancer types including HPV-positive HNSCC, while targeting specific signalling pathways such as BRD4 could provide a better and potentially new treatment to improve HNSCC therapeutic outcome." (PMID 36333293, 2022).